EGFR (epidermal growth factor receptor)
Diseases named in the same sentence as EGFR in open-access papers (continued):
Sharing a sentence is not in itself a finding about the gene and the disease.
tumor (continued). "Furthermore, we uncovered that tumor-intrinsic B7-H3 expression enhanced cell growth and tumor growth via the EGFR signaling pathway in vitro and in vivo." (PMID 38370387, 2024). "All tumours were adenocarcinoma histology; 13 (81.3%) had EGFR mutations, and 3 (18.8%) had no targetable mutations." (PMID 39816395, 2024). "The heterogeneity within the tumor may impact the response to EGFR-TKI, as adenocarcinoma and squamous components may respond differently to treatment." (PMID 39026979, 2024). "EGFR activity enhances tumor growth, invasion, and metastasis." (PMID 38664641, 2024). "Cetuximab, an EGFR inhibitor, showed a strong correlation with increased tumor response." (PMID 39050571, 2024). "Furthermore, EGFR alterations have been widely reported across various tumor types, including lung, breast, gastrointestinal tract, and GBM, and have been associated with increased tumorigenesis." (PMID 38491408, 2024). "This may therefore suggest that the DDIR-negative tumours with high EGFR RNA expression are EGFR-driven and targetable." (PMID 38744099, 2024). "Regarding false negative results from multi-gene panel tests related to tumor content, several reports have compared the ODxTT with single-gene tests for EGFR mutations." (PMID 38730622, 2024). "Thus, CRC-derived organoid cultures are a smart model for studying the tumor microenvironment and for the preclinical assay of anti-EGFR drugs." (PMID 39000238, 2024). "In addition, inhibition of epidermal growth factor receptor (EGFR) significantly reduced the tumor burden." (PMID 38637998, 2024). "Based on the results, anti-EGFR QDM capturing therapeutic siRNA could be suggested as an alternative modality for tumor-targeted theranosis." (PMID 38892434, 2024). "It has been shown that in addition to cytotoxic CT (cytotoxic T cell), anti-VEGF (anti-vascular endothelial growth fator) and anti-EGFR (anti-epidermal growth factor receptor) normalize tumor vascularization, thereby increasing the delivery of CT to tumor cells." (PMID 39475884, 2024). "Furthermore, the study investigated the impact of various tumor markers, including tumor abnormal protein (TAP) and carcinoembryonic antigen (CEA), on EGFR mutation status." (PMID 38980474, 2024). "EGFR and TROP2 are co-expressed in many solid tumors, and co-targeting these receptors may improve tumor selectivity compared with EGFR or TROP2 monospecific ADCs." (PMID 39065587, 2024). "Polarization of murine macrophages towards an M1-like phenotype demonstrated cytotoxic effects and slowed tumor progression in peritoneal tumor models, whereas M2-like macrophages were shown to promote tumor dissemination in gastric cancer via EGFR signaling pathways." (PMID 38504975, 2024). "Notably, CMS2-associated WNT and VEGF pathways displayed a more consistent distribution of their activities across tumor regions as compared to the activity of EGFR and MAPK pathways." (PMID 38200223, 2024). "The modified NK cells had increased cytokine secretion; they preferentially targeted and killed tumor cells that overexpressed EGFR in a wide variety of tumor types, and they could infiltrate tumors effectively apparently with minimal side effects." (PMID 39763648, 2024). "The expression of EGFR was observed in the fetal component of tumor tissues by scRNA-seq." (PMID 39567475, 2024). "Previous evidence suggests that anti-epidermal growth factor receptor (EGFR) therapies may enhance tumor response and trigger an immunogenic apoptosis cascade that is usually associated with increased expression of CTLA4 and PDL1." (PMID 39080202, 2024). "Mapping expression levels of EGFR L858R across clones within the same tumor along with their levels of proliferation may provide important insights for predicting and monitoring response to anti-EGFR treatment in NSCLC patients." (PMID 39061010, 2024).
tumor (continued). "Benmelstobart plus anlotinib showed promising anti-tumor efficacy with tolerable safety profile, supporting the value of further development of this convenient chemotherapy-free regimen for patients with EGFR-positive advanced NSCLC who progressed after EGFR TKI therapy." (PMID 39389963, 2024). "The EGFR pathway’s interaction with integrin activates matrix metalloproteinases, modifying cell adhesion, stimulating cell motility and invasion, and promoting tumour metastasis." (PMID 38389925, 2024). "The CONAN-1 inhibits tumor expansion less effectively than the EGFR-targeting antibody (cetuximab)." (PMID 38191571, 2024). "EGFR Y891D is a rare non-activating variant, identified in only one tumor in the AACR Project Genie database." (PMID 38182677, 2024). "Deep learning (DL) has been applied in many clinical areas such as tumor pathology with high accuracy while DL algorithms predicting EGFR mutation status in BM are not available." (PMID 38169047, 2024). "Additionally, EGFR-TKI resistance in tumor cells is closely related to reactive oxygen species (ROS)." (PMID 39451714, 2024). "Primary tumor location has implications for the potential treatment of CRC with anti-EGFR therapy." (PMID 38409377, 2024). "Genetic alterations in migratory tumor cells, such as EGFR gains, might enhance their aggressive phenotype and foster intricate cell–cell interactions with iCAFs." (PMID 38892065, 2024). "Disruption of the interplay between α5β1 integrin and EGFR signaling may be an effective means of reducing tumor cell motility and metastasis." (PMID 38315147, 2024). "Keyword analysis indicated that in recent years, a substantial body of research has concentrated on paronychia issues caused by epidermal growth factor receptor inhibitors (EGFRI)-class drugs, such as Gefitinib, Erlotinib, and Afatinib, in the context of tumor treatment." (PMID 39331909, 2024). "Our work demonstrates that a combination of anti-TGF-β and anti-PD-1 significantly inhibits the growth of EGFR-TKI resistant tumor cells both in vitro and in vivo, highlighting the potential of combination therapy for patients after failure of EGFR-TKI treatment." (PMID 39004699, 2024). "Previous studies have shown that the overall immunotherapeutic efficacy of driver mutation-positive NSCLC agents, such as EGFR, is unsatisfactory, possibly because of the local immune-negative microenvironment of the tumor after EGFR TKI resistance." (PMID 39267851, 2024). "In hyper-progression, EGFR mutations are likely oncogenic drivers that accelerate tumor growth, independent of immune activity." (PMID 39902124, 2024). "However, anti-EGFR targeted therapies have been less successful than expected due to acquired drug resistance and tumour heterogeneity, with only marginal increase in clinical benefits as monotherapy for GBM patients." (PMID 38615034, 2024). "The analysis of circulating tumor DNA from NSCLC patients reveals that 46% of patients treated with EGFR-TKIs may have multiple resistance mechanisms." (PMID 38402169, 2024). "CD109 interacts with EGFR to activate the Akt/mTOR pathway, driving tumor growth." (PMID 39990858, 2024). "Positive PD-L1 staining (P = .0426) and tumor mutational burden elevation (P = .0264), as well as KRAS mutations, were more frequent in the LITT + ICB group, while tumors were more frequently driven by EGFR or ALK in the LITT-only group (P = .0021)." (PMID 39717437, 2024). "Additionally, the expression level of EGFR was significantly different between normal and tumor tissues (P ≤ 0.05), with a marked increase in expression observed in tumor samples." (PMID 39720087, 2024). "Conversely, HER2, TOPO II, and EGFR were significantly associated with pCR rates but did not demonstrate correlations with changes in tumor size." (PMID 38509525, 2024).
tumor (continued). "To validate this clinically, we showed that EVs derived from primary tumour cell line of a patient with secondary resistance to osimertinib could confer resistance an osimertinib sensitive EGFR T790M positive cell line." (PMID 39431017, 2024). "Interestingly, one of the main targets of this miRNAs cluster is FOXO1, a pro‐apoptotic gene, which appeared to be repressed in EGFR‐amp tumours." (PMID 39148319, 2024). "Notably, EGFR-expressing tumours were enriched in proliferative endothelial cells, while EGFR-KO tumours contained mostly angiogenic endothelia." (PMID 38570528, 2024). "Membranous EGFR staining was observed in varying percentages of tumor cells, ranging from 0 to 99%." (PMID 39405290, 2024). "However, the proportion of tumor cells with higher intensity of EGFR expression was significantly greater in the pembrolizumab group." (PMID 38916448, 2024). "To circumvent and overcome the limitations of monoclonal antibody therapy targeting EGFR alone in patients with GBM, we designed this phase I study based on our preclinical data that showed that the arming of ATC with EGFR BiAb exerts potent in vitro anti-tumor activity." (PMID 38263486, 2024). "TMB was higher in TRIM56 high expression group, and the tumor mutation microlandscape of TRIM56 high expression group and low expression group showed that EGFR and PTEN mutation proportion in high expression group was significantly higher than that in low expression group." (PMID 38348047, 2024). "Given that tumor progression in HNC cancers is predominantly governed by EGFR and the downstream signaling pathways mediated by this receptor, we hypothesized that bufalin might influence tumor proliferation and progression by acting on such receptor." (PMID 39123466, 2024). "The increased frequency of a myeloid-rich stroma may be due to HER2xHER2 and EGFRxHER2 T-BsAbs effectively driving the elimination of EGFR+HER2+ tumor cells while sparing EGFR−HER2− stromal cells." (PMID 38650005, 2024). "Specifically, the addition of bosentan to gefitinib, an EGFR inhibitor, was found to significantly improve tumor perfusion and drug delivery, in addition to successfully reducing tumor size and preventing tumor recurrence compared to treatment with gefitinib alone." (PMID 38785410, 2024). "Moreover, clinical trials of EGFR-targeted therapies have demonstrated limited efficacy, partly due to tumor heterogeneity and acquired resistance mechanisms." (PMID 39184354, 2024). "This activation promotes tumor progression and confers resistance to EGFR‐TKIs." (PMID 38867713, 2024). "For passive tumor targeting, we have created a functionalized siRNA delivery approach, GE11-siRNA-CSNPs, for targeting and inhibiting miRNA-21 expression as a method to effectively cause death in TNBC cells that overexpress the EGFR." (PMID 38592437, 2024). "Research of downstream pathways could elucidate a way to safely and synergistically inhibit tumor cells with EGFR inhibitors." (PMID 38396993, 2024). "The designed drug delivery system offers a highly controlled and targeted therapeutic approach, effectively inhibiting tumor growth, suppressing bypass signaling pathways, and overcoming EGFR-TKI resistance, thus offering a potential solution for maximizing therapeutic benefits." (PMID 39321294, 2024). "EGFR-TKIs specifically target and act on tumor cells with precision." (PMID 39196297, 2024). "Ground-glass opacity (GGO) was frequently observed in patients with EGFR-positive tumors, and the proportion of GGO within the tumor was significantly greater in patients with 21L858R mutations compared to those with 19Del deletions and those with the wild-type gene." (PMID 39834943, 2024). "In EGFR-TKI therapy for EGFR mutation-positive patients, it has been suggested that there is a survival benefit to administering a TKI if the patient remains clinically stable after radiological tumor progression." (PMID 39156250, 2024).
tumor (continued). "In addition, both nanoparticle formulations were functionalized with an antibody against the epidermal growth factor receptor (EGFR) to enhance tumor cell targeting." (PMID 39204314, 2024). "Notably, by designing viral particles with anti-EGFR cetuximab and CCL5 chimeric receptors (OV-Cmab-CCL5), Tian and colleagues were additionally able to promote the specific infiltration of various immune cells to EGFR-positive GBM tumours." (PMID 38615034, 2024). "The potency (i.e. EC50 for degranulation and tumor lysis) of the EGFR-Vδ2hi-lo bsVHH-albumin construct was ~10 fold lower compared to the EGFR-Vδ2hi-lo bsVHH-Fc perhaps as a result of impaired immune synapse formation when albumin was bound to the engager in this specific orientation." (PMID 39493452, 2024). "For example, EGFR plays an important role in the growth and reproduction of tumor cells, and ESR1 can cause abnormalities in the estrogen signaling pathway, thereby affecting the growth and metastasis of tumor cells." (PMID 39457402, 2024). "At the end of erlotinib treatment, plasma genotyping was conducted to guide the switch in therapeutic strategy due to the lack of tumor tissues, and this testing confirmed the presence of EGFR L858R mutation." (PMID 39135785, 2024). "In addition, in the 3D spheroid model, the EGFR-targeted ICED-N increased tumor accumulation with 513-fold greater targeting efficacy to MG-63 (EGFR+) cells than the control fibroblast (EGFR−) cells." (PMID 38338373, 2024). "The most frequent EGFR modification in tumor cells is overexpression." (PMID 39000238, 2024). "Due to its overexpression in tumor cells, EGFR is an important target in cancer therapy." (PMID 39138197, 2024). "However, the intricate nature of tumor biology, marked by heterogeneity and genomic instability, poses a significant challenge in the form of anticancer drug resistance, particularly with EGFR inhibitors." (PMID 39130636, 2024). "We observed milder EGFR expression in both younger and older patients, while those aged 50–70 exhibited higher expression levels, which may indicate more aggressive tumor growth and a poorer prognosis in this age group, as reflected in the literature." (PMID 39459468, 2024). "This suggests that the tumor with high EGFR expression may be unresponsive to immunotherapy by disturbing essential mechanism and subsequent loss of functionality in cytotoxic T and NK cells in the TME." (PMID 38916448, 2024). "The mechanism by which the combination of antiangiogenic drugs and EGFR-TKIs provides benefits may stem from the ability of antiangiogenic agents to normalize blood flow in tumor blood vessels, thereby enhancing drug delivery and concentration within tumors." (PMID 39533233, 2024). "To ascertain whether the diminished antitumor activity of αEGFR-mIL12mut2 stemmed from weaker tumor binding, we quantified the number of EGFR on MC38-EGFR5 tumor cells, revealing a significantly higher count compared to PD-1 on intratumoral CD8+T cells." (PMID 38830882, 2024). "Finally, heterogeneous populations of microglia and myeloid cells were also detected and varied between tumours with different EGFR status, while oligodendrocytes and their precursors (OPCs) did not exhibit major differences in this regard." (PMID 38570528, 2024). "However, in 2019, our group reported that a histidine-rich peptide, rLj-112, inhibits tumor activity by binding to and internalizing EGFR on the cell surface." (PMID 39519855, 2024). "Suppression of DUSP5 impeded tumor metastasis and EGFR-TKI resistance in LUAD cells." (PMID 38872157, 2024). "Therefore, CD73 emerges as a novel target for the treatment of NSCLC with EGFR mutation and inhibiting CD73 to promote STING induction in tumor cells offers a new strategy for NSCLC treatment." (PMID 38566036, 2024).
tumor (continued). "The discoveries of tumor-driver genes such as epidermal growth factor receptor (EGFR), anaplastic lymphoma kinase (ALK), mesenchymal-epithelial transition (MET), and c-ros oncogene 1 (ROS1) in NSCLC have recommended TKIs as the first-line option for patients with advanced stage disease." (PMID 38927911, 2024). "Moreover, we report high rates of EGFR mutations and a numerically reduced median survival in patients with high serum CEA and spiculated tumor contours." (PMID 39407771, 2024). "The two variables showed a correlation of 0.3708 (p = 0.00679), indicating that higher EMP in tumor tissue corresponded to a higher frequency of EGFR mutations in DNA, despite not showing a strong correlation." (PMID 39358807, 2024). "We found that AREG_EGFR interaction exclusively occurred between migratory tumor and IL6high iCAF." (PMID 38892065, 2024). "In this manuscript, we performed a relatively large-scale study to determine the correlation between the percentage of tumor cellularity estimated by certified anatomic pathologists and VAFs of well-studied driver mutations detected in key oncogenes (i.e., BRAF, EGFR, KRAS, and NRAS)." (PMID 38397405, 2024). "Tumor heterogeneity and evolution have necessitated resampling with liquid biopsy mutations that confer resistance to treatments such as RAS mutations in those receiving anti-EGFR therapy." (PMID 39199569, 2024). "It was observed that patients harboring EGFR mutations exhibited higher levels of p-EGFR within tumor tissues as opposed to those with the wild-type allele." (PMID 39062533, 2024). "Interestingly, GSC tumour cells, clustered separately, revealing distinct cellular landscapes dependent on the EGFR status." (PMID 38570528, 2024). "Animal trials conducted using an orthotopic TNBC xenograft tumors model in mice demonstrated that RNA nanoparticles incorporated with the anti-EGFR aptamer could specifically target tumors and effectively inhibit tumor growth." (PMID 38675202, 2024). "Correlations between EGFR and KRAS mutation subtypes and PD-L1 tumor proportion score." (PMID 38394518, 2024). "Consequently, the predicted anti-tumor mechanisms of EGFR include cell cycle arrest, the promotion of apoptosis, inhibition of tumor invasion and metastasis, and anti-angiogenesis." (PMID 39598341, 2024). "The benefit provided by EGFR mAbs in KRAS WT mCRC is associated with left-sided primary tumour location, younger patient age and absence of NRAS or BRAF mutations." (PMID 38402342, 2024). "Moreover, activation of EGFR can increase pSTAT3 level, indicating that there is a positive feedback loop between EGFR and pSTAT3, which contributes to tumor malignancy." (PMID 39967270, 2024). "Taken together, this data suggests that even within the same tumor, anti-EGFR treatment may be more effective in clones with lower proliferation rates and lower expression of the mutant form of the EGFR." (PMID 39061010, 2024). "TCR clonality was also reduced in EGFR mutant tumors in comparison to other tumor types." (PMID 39272973, 2024). "The anti-EGFR conjugation enhances precision by allowing specific recognition and binding to cancer cells, while the composite incorporates Mn core phthalocyanine for precise tumor imaging and real-time treatment monitoring." (PMID 39525484, 2024). "In order to specifically address Iren-AuSiO2_COOH to target tumor/stromal cells, conjugation with the EGFR CL4 (Iren-AuSiO2_CL4) or PDGFRβ Gint4.T (Iren-AuSiO2_Gint4.T) aptamers, and dual functionalization with both CL4 and Gint4.T (Iren-AuSiO2_CL4_Gint4.T) were performed." (PMID 38532439, 2024). "The tumor clearance was slower, indicating some interaction/retention with EGFR." (PMID 38363422, 2024). "The elevated expression of TGF-α, which is a ligand binding to the EGFR, was associated with a poor prognosis for EGFR-mutated LUAD but not for wild-type LUAD, and TGF-α promoted the tumor growth of EGFR-mutated lung tumors in mice." (PMID 38398101, 2024).